BCL2 (BCL2 apoptosis regulator)
Diseases named in the same sentence as BCL2 in open-access papers (continued):
Sharing a sentence is not in itself a finding about the gene and the disease.
hepatocellular carcinoma (continued). "Additionally, the nuclear expression of Bcl-2 and Twist1 is correlated with poor survival in hepatocellular carcinoma." (PMID 28032603, 2017). "Although the mechanism of how these limonoids interfere with the NF-κB signaling pathway has to be investigated in more detail, our results indicate that TR4 and TR9 reduce NF-κB activity in hepatoma cells, resulting in decreased expression of NF-κB targets (Cyclin D1, Bcl2 or A20)." (PMID 27518192, 2016). "Thus while over-expression of Bcl-2 promotes lymphoma by suppressing apoptosis, the same maneuver suppresses carcinogen-induced hepatocellular carcinoma (HCC), likely by suppressing proliferation." (PMID 27196317, 2016). "Moreover, miR-34a mRNA level is negatively correlated with Bcl-2 protein level and directly modulates Bcl-2 expression in hepatocellular carcinoma (HCC)." (PMID 27514646, 2016). "Luteolin also been reported to induce apoptosis in other types of cancer cells (such as, hepatocellular carcinoma cells, colorectal cancer cells and pancreatic carcinoma cells) through activating Casepase-3, increasing Bax and decreasing BCL-2 protein expression levels." (PMID 25901161, 2015). "In addition, IFN α with sorafenib together downregulates the expression of Mcl-1, Bcl-2 and Bcl-xL, resulting in hepatocellular carcinoma (HCC) cell apoptosis." (PMID 26452032, 2015). "In addition, P21 also plays an important role in regulation of apoptosis where overexpression of P21 in human hepatoma cell lines induces the expression of Bax and suppresses the anti-apoptotic effect of Bcl-2 through modulating the ratio of Bcl-2 to Bax29." (PMID 26492952, 2015). "On the other hand, CD133 was shown to confer chemoresistance by activation of the AKT/PKB and Bcl-2 cell survival response in hepatoma cells, and suppression of the Hedgehog pathway could also sensitize the hepatoma cells to chemotherapeutic agent." (PMID 23097677, 2012). "Nuclear translocation of NF-κB may up-regulate prosurvival factor Bcl-2 in tumor cells, as observed in human hepatoma cells." (PMID 20975993, 2010). "Bcl-2 expression is significantly elevated in hepatocellular carcinoma (HCC) tissue at both the mRNA and protein levels, and this overexpression is strongly associated with increased tumor cell." (PMID 40841912, 2025). "Our work demonstrated that lipase might be an ideal anticancer candidate, specific to cancer cells, for treating hepatocellular carcinoma (HepG-2) by its necrotic and apoptotic activities in addition to its effect in inducing downregulation (62%) of Bcl-2 gene." (PMID 40057735, 2025). "In this context, a previous study shows that KAT2B plays a tumor suppressive role in hepatocellular carcinoma (HCC) via regulating GLI1/BCL2 signaling pathway." (PMID 38641672, 2024).
hepatocellular carcinoma (continued). "After Bclaf1 knockout, Bcl-2 expression was downregulated, Bax expression was increased, and the Bcl-2/Bax ratio was decreased versus the control findings (p < 0.01), indicating that mitochondrial apoptosis was induced in human hepatoma cells after Bclaf1 knockout." (PMID 39444606, 2024). "In the PI3K activator group, the vitality and Bcl-2 protein expression level of HuH-7 hepatoma cells increased significantly (P < 0.05), while the apoptosis rate and Caspase-3 and Bax protein expression levels of hepatoma cells decreased significantly (P < 0.05)." (PMID 35909586, 2022). "Obatoclax, a Bcl-2 inhibitor, directly inhibits the proliferation of hepatocellular carcinoma (HCC) cells and sensitizes cancer cells to T cell-mediated killing." (PMID 35990696, 2022). "However, the high expression of IL-32β was increased in cancer tissues and serum in patients with hepatocellular carcinoma, and the inhibition of IL-32α expression using siRNA resulted in decreased expression of the antiapoptotic protein bcl-2, inhibiting cell growth and apoptosis." (PMID 34682815, 2021). "Moreover, the results from flow cytometric analysis showed that overexpression of Bcl‐2 might result in a decrease of the percentage of apoptotic cells induced by ATRA in both of the two hepatoma cell lines." (PMID 33090723, 2020). "The direct repression of BCL2 by miR-125b has also been demonstrated in hepatocellular carcinoma (HCC), in which it suppresses HCC cells proliferation and induces apoptosis." (PMID 29361709, 2018). "Therefore, the well-known decrease of MCL-1 induced by sorafenib, combined to BCL-xL/BCL-2 reduction by RNA silencing or ABT-263 treatment, could be enough to cause hepatoma cell death as previously reported." (PMID 29682179, 2018). "Overexpression of Bcl-2 may protect human hepatoma cells from antibody-mediated apoptosis." (PMID 25605484, 2015). "Overexpression of Bcl-2 also may protect human hepatoma cells from antibody mediated apoptosis." (PMID 25723613, 2014). "A recent study demonstrated that treatment of the hepatoma cell lines HepG2 and Bel7402 with germacrone promoted cell apoptosis, associated with the upregulation of bax and the downregulation of bcl-2, indicating that germacrone may have a potential role in the treatment of hepatocellular carcinoma." (PMID 25289068, 2014). "In hepatocellular carcinoma cells (HCC), combination of survivin and Bcl-2 inhibitors led to large apoptotic effect." (PMID 25140197, 2014). "This persistent infection is strongly linked to hepatic sclerosis, hepatitis, cirrhosis, and hepatocellular carcinoma (HCC), where elevated Bcl-2 expression in liver diseases can lead to the development of HCC." (PMID 25699089, 2014). "miR-125b was also able to block cell proliferation in hepatocellular carcinoma (HCC) by targeting the anti-apoptotic protein Bcl-2." (PMID 23325049, 2013). "In another example, the forced expression of miR-29 sensitized hepatocellular carcinoma (HCC) cells to apoptosis under serum starvation and hypoxia conditions through a mitochondrial pathway involving Mcl-1 and Bcl-2." (PMID 23509776, 2013). "HCC data was assessed using survival analysis to measure PTEN, PI3K/AKT/mTOR pathway, β-catenin/BCL2, and β-catenin/HSP90 effect on prognosis of hepatocellular carcinoma patients using Kaplan–Meier (KM) plots." (PMID 40456804, 2025).
hepatocellular carcinoma (continued). "Similarly, de novo triglyceride (TG) synthesis driven by glycerol‐3‐phosphate acyltransferase 3 can stimulate the NF‐κB/BCL‐2 antiapoptotic signaling pathway, leading to the resistance of hepatocellular carcinoma (HCC) cells to sorafenib treatment." (PMID 40919131, 2025). "In hepatocellular carcinoma, trifluoperazine increases FOXO1 nuclear expression, elevating Bax levels and reducing Bcl-2, thereby raising the Bax/Bcl-2 ratio to promote apoptosis." (PMID 40718442, 2025). "OA activates apoptosis in the hepatocellular carcinoma (HCC) cells SMMC-7721 and BEL-7404 by altering the Bax/Bcl2 balance, inducing the release of cytochrome-c and activating caspase-9 and caspase-3." (PMID 39064870, 2024). "FAD induces caspase-dependent apoptosis through an increase in BAX and cleaved caspase-3 and a decrease in BCL2, RAB51, BRCA1, and MDC1 in hepatocellular carcinoma." (PMID 39765861, 2024). "In hepatoma cells, BDH2 can promote mitochondrial apoptosis by upregulating the pro-apoptotic protein Bax and downregulating the anti-apoptotic protein Bcl-2 and can also induce apoptosis of liver cancer cells through a caspase 3-independent pathway." (PMID 39691718, 2024). "As a result, STAT3-regulated genes Bcl-2, cyclin D1, Bcl-xL, survivin, Mcl-1, and VEGF were downregulated, inhibiting proliferation and prompting substantial death in hepatocellular carcinoma cells." (PMID 38310190, 2024). "In hepatocellular carcinoma, PCSK9 was found to promote cell growth by inhibiting cell apoptosis via the involvement of the Bax/Bcl-2/Caspase-9/Caspase-3 pathway." (PMID 38611089, 2024). "In mouse hepatoma (Hepa-1) and human hepatoblastoma (HepG2) cells, NRF2 activation upregulated the antiapoptotic protein Bcl-2, prevented apoptosis, and increased tumor cell survival and growth/proliferation." (PMID 37511764, 2023). "Amygdalin has been demonstrated to stimulate the apoptotic process by upregulating caspase-3 expression and downregulating Bcl-2 expression, as well as inhibiting HepG2 and EAC hepatocellular cancer cell proliferation and upregulating Beclin-1 expression." (PMID 37762572, 2023). "Treated hepatocellular carcinoma with an IC50 of GL extract (47.5 ug/ml) upregulates pro-apoptotic BAX and downregulates anti-apoptotic BCL2, which disrupts the BAX/BCL2 ratio, leading to activation of caspase 3 inside treated HepG2 cells." (PMID 37127764, 2023). "The results confirmed the synergistic effect on apoptosis, proliferation, and angiogenesis of hepatocellular carcinoma (HCC), by the increase in Caspase-3 and Bax/Bcl-2 ratio and the decrease in C-myc and VEGF." (PMID 37111802, 2023). "A combinatorial effect of ABT-263, an inhibitor of Bcl-2, Bcl-XL, and Bcl-w, together with anti-angiogenic TKI’s was already reported in HepG2 liver carcinoma cell lines in vitro." (PMID 37620408, 2023). "Western Blot experiments were performed to detect the expression of hepatoma cell apoptosis-related proteins: Caspase9, Caspase3, PARP, Bax, and anti-apoptotic protein, Bcl-2." (PMID 35972600, 2022).
hepatocellular carcinoma (continued). "The DHA, as functional excipient, was used to synthesize nanoparticles for reversing drug resistance in hepatocellular carcinoma (HCC) via suppressing drug-resistant proteins MRP, LRP, BCRP, and Bcl-2." (PMID 35616278, 2022). "Another study indicates that knockdown of CBS can induce the increase in the Bax/Bcl-2 ratio, activation of caspase-3 and PARP in human hepatoma SMMC-7721 cells." (PMID 35795862, 2022). "Heteronemin enhanced the rate of ROS, Bax, SOD2, and caspase-8 production, which decreased the level of Bcl-2 and SOD1 in human hepatocellular carcinoma cells." (PMID 36286449, 2022). "In hepatoma cells, CD147 was also shown to protect cells from apoptosis by upregulating Bcl2 levels and promoting ERK signaling." (PMID 35892564, 2022). "In human hepatoma (SMMC-7721) cell lines, icariin initiated the mitochondrial-dependent apoptotic pathway by increasing the Bax/Bcl-2 ratio, dysfunctioning of mitochondrial membrane potential to make the release of cytochrome C and activating caspase cascade." (PMID 34768743, 2021). "Additionally, CPE treatment of hepatocellular carcinoma (HCC) MHCC97H cells during metabolic stress has been shown to mediate survival by up-regulating anti-apoptotic protein BCL-2 and other pro-survival genes through activation of the ERK1/2 pathway." (PMID 31798768, 2019). "PCAF can induce cell apoptosis by modulating the GLI1/BCL-2/BAX axis or by acetylating histone H4 and inactivating AKT signaling, which in turn suppresses hepatocellular carcinoma progression." (PMID 30833716, 2019). "Our in vitro data indicates that regorafenib also increases the BCL-2/MCL-1 ratio and ABT-263 administration is able to sensitize hepatoma cells against regorafenib." (PMID 29682179, 2018). "Considerable evidence supports the idea that enhanced Bax/Bcl-2 ratio, combined with cleavage of caspase-3, takes place in various liver diseases, including chronic hepatitis, alcoholic liver, and hepatocellular carcinoma (HCC)." (PMID 30217028, 2018). "Although no direct links between OPN3 and 5FU treatment have been identified in normal cells, in hepatocellular carcinoma cells, OPN3 is involved in regulating 5FU-induced apoptosis via control of the phospho-Akt/total Akt and Bcl2/Bax ratios." (PMID 29950993, 2018). "Meanwhile, we determined the expression levels of Bcl‐2 and Bax to understand the effect of CNPs‐AL‐PEG600 at a low concentration on apoptosis‐related proteins in human hepatoma cells." (PMID 28070935, 2017). "(A-C) Correlation analysis of miR-500a-3p expression and Bcl-2, Bcl-xL and MCL1 mRNA expression levels in 8 fresh human hepatocellular carcinoma tissues." (PMID 28750679, 2017). "Although the expression of Bax showed little change, the ratio of Bcl‐2 to Bax increased significantly which represents apoptosis of tumor cells 7, and this suggested that the CNPs‐AL‐PEG600 reduced apoptosis in human hepatoma cells." (PMID 28070935, 2017). "Icaritin triggers the mitochondrial/caspase apoptotic pathway, by decreasing the Bcl-2/Bax protein ratio and increasing activation of caspase-3 in SMMC-7721 hepatoma cells." (PMID 27835879, 2016). "In hepatocellular carcinoma cells, TM not only reduced the dissipation of MMP, but also suppressed Bcl-2 levels and enhanced the expressions of Bax and Bad." (PMID 28018916, 2016). "ART has been shown to induce apoptosis, activate caspase-3 and increase the Bax/Bcl-2 ratio and poly (ADP-ribose) polymerase in both human hepatoma cells multiple myeloma and diffuse large B-cell lymphoma (DLBCL)." (PMID 25738364, 2015). "First, carnosic acid induced down-regulation of Bcl-2 and c-FLIP expression, and up-regulation of DR5, Bim, and PUMA expression in human renal carcinoma ACHN cells and human hepatoma SK-Hep1 cells." (PMID 25596735, 2015). "The overexpression of Bcl-2 and IAP-2 has been identified in a variety of human cancers and it has been reported that miR-29s target Bcl-2 in both hepatocellular carcinoma (HCC) and OS cell line." (PMID 25174983, 2014).
hepatocellular carcinoma (continued). "Other studies showed in hepatocellular carcinoma cell lines that PTK787 treatment alone reduced AKT-phosphorylation, Cyclin D1 and anti-apoptotic Bcl-2 protein expression, which correlated with cell cycle retardation/arrest and reduced cell growth." (PMID 25340839, 2014). "Our study aims to study the therapeutic effects of a novel Bcl-2 inhibitor, ABT-263, on hepatocellular carcinoma (HCC) and to provide primary preclinical data for future clinical trial with ABT-263." (PMID 21829603, 2011). "Furthermore, an in vivo study revealed that after injecting a hepatocellular carcinoma rat model with ZSC leaf extract, a significant downregulation of the anti-apoptotic protein Bcl-2 was observed, which enhanced apoptosis and tumor shrinkage." (PMID 39859369, 2025). "Thus, modulation of PI3K/AKT/mTOR pathway through enhanced PTEN, as well as reduced β-catenin/BCL2 and β-catenin/HSP90 expression leads to significantly better survival probability in hepatocellular carcinoma samples." (PMID 40456804, 2025). "Similarly, in hepatocellular carcinoma (HCC), trifluoperazine induces G0/G1 arrest and apoptosis by increasing the Bax/Bcl-2 ratio, effectively reducing cell viability." (PMID 40718442, 2025). "In glioblastoma, breast cancer, and hepatocellular carcinoma (HCC), PRMT2 acts as a putative oncogene, with its high expression promoting cell proliferation and inhibiting apoptosis through catalyzing H3R8me2a (such as activating Bcl2 expression)." (PMID 41154773, 2025). "In vivo, combined treatment with Apigenin and 5-FU confirmed significant growth inhibition of hepatocellular carcinoma (HCC) xenograft tumors via activation of the mitochondrial pathway of apoptosis, indicated by activation of caspase 3 and PARP and a decrease in Bcl-2 levels." (PMID 38791608, 2024). "Liu demonstrated in hepatocellular carcinoma cell lines that nEGFR can affect cell apoptosis by stimulating the expression of SOS1, which then activates the HRAS/PI3K/AKT pathway, leading to nuclear translocation of p-AKT and Bcl-2." (PMID 36982894, 2023). "In hepatoma HepG2 cells, TSAIII treatment is reported to activate cleaved-caspase-3, caspase-8, and caspase-9, increase the expression of Mcl-1 and Bcl-2, and induce the release of cytochrome C, suggesting that TSAIII induces caspase-dependent and mitochondrial-mediated apoptosis." (PMID 36611961, 2022). "Similarly, paeoniflorin stimulated apoptosis in hepatocellular carcinoma (HCC) cells via inhibition of prostaglandin E receptor EP2, elevation of the Bax-to-Bcl-2 ratio, and activation of caspase-3." (PMID 33531900, 2021). "Similarly, ropivacaine has been found to activate the caspase 3 signaling pathway in hepatocellular carcinoma, and ropivacaine can activate the cleaved PARP and decrease Bcl-2 protein to induce apoptosis in other cancer cells." (PMID 34696683, 2021). "Its mechanism might be partially related to apoptosis induction in hepatocellular carcinoma cells by downregulating prostaglandin E receptor EP2 levels, increasing the Bax/Bcl-2 ratio and thus upregulating the activation of caspase-3." (PMID 32410996, 2020).